IRF1 (interferon regulatory factor 1)
Diseases named in the same sentence as IRF1 in open-access papers (continued):
Sharing a sentence is not in itself a finding about the gene and the disease.
viral infection (continued). "Interestingly, while IRF3 nuclei translocation occurred exclusively in infected cells, we observed that IRF1 accumulation in the nuclei occurred mostly in bystander cells, confirmed by ZIKV dsRNA staining, which shows the early stage of virus infection." (PMID 36311766, 2022). "Among the upregulated ISGs, 27 ISGs, including IRF1, IRF7, IFITM1, and IFITM3, play antiviral roles in different stages of virus proliferation, thus inhibiting or delaying the process of virus infection by interacting with other proteins or ISGs to form a complex protein–protein interaction network." (PMID 35401515, 2022). "Viral infection activates NF-κB, MAPK, and JAK-STAT1/2 signaling, which may synergistically induce the IRF1 transcription." (PMID 35972291, 2022). "IRF1 transcriptionally induced by the phosphorylated STAT1 and stabilized by XAF1 further facilitates the induction of the IRF1 target genes such as DDX58, DDX60, MX1, and OAS2 during viral infection." (PMID 35972291, 2022). "As previously reported, IRF1 could be induced by many cytokines such as IFNs (-α, -β, -γ), TNF-α, IL-1, IL-6, LIF and virus infection mediated by STAT and NF-κB." (PMID 34930359, 2021). "Despite general recognition of the importance of IRF1 to antiviral responses, the molecular mechanisms by which IRF1 is regulated during viral infections are not well understood." (PMID 34248923, 2021). "Meanwhile, we found that IFNs could significantly trigger the production of a variety of IFN-induced genes (IFIT1, IFITM3, Mx-1, OASL, ISG15, PKR, GBP1, Viperin, BST2, IRF-1, and CXCL10) and MHC molecules, which play key roles in resistance to virus infection." (PMID 32655518, 2020). "Interferon regulatory factor 1 is the prototype member of a family of nine transcription factors and is expressed in a variety of cells in which plays a crucial role in promoting the expression of type I IFN genes following viral infection." (PMID 29545793, 2018). "IRF1 is a known regulator of type I IFN expression and is responsive to IFNγ and viral infection." (PMID 27966453, 2017). "The results showed that expression levels of mViperin and IRF-1 in Marc-145 cells infected with PRRSV BB0907 strain are simultaneously increased compared with those without the virus infection." (PMID 27232627, 2016). "Although IRF-1 has been characterized as a substrate of the ubiquitination machinery, an E3 ligase capable of mediating IRF-1 ubiquitination during virus infection had not been identified." (PMID 27795392, 2016). "With IRF1 knock down, a significant increase in EBOV GP/rVSV RNA was observed 24 hours following infection, consistent with the importance of IRF1 expression in controlling virus infection by IFNγ." (PMID 26562011, 2015). "As one of the ISGs, IRF1 is not a direct-acting antiviral effector but a typical modular against virus infections." (PMID 26593937, 2015). "Although IRF-1 was originally identified as an IFN inducer upon virus infection, the antiviral effect of IRF-1 was not due to a hampered type I IFN response." (PMID 24675692, 2014). "Therefore, IRF-1 plays a dual role in regulating the induction of apoptosis and PSR during viral infection, and apoptosis precedes and subsequently promotes PSR expression." (PMID 25342322, 2014). "Type I IFN induction in TKO macrophages could be mediated in part by IRF-1, which regulates expression of antiviral genes independently of type I IFN in the context of several other viral infections." (PMID 23300459, 2013). "Furthermore, RelAp43 stimulates the expression of HIAP1, IRF1, and IFN-β - three genes involved in cell immunity against viral infection." (PMID 23271966, 2012). "Moreover, IRF-1-/- CD8+ T cells were fully capable of lysing target cells and clearing viral infection from neurons and the brain." (PMID 21909274, 2011).
viral infection (continued). "Other experiments suggested that IRF-1 activation also regulated genes that directly limit replication of several viruses (encephalomyocarditis (EMCV), NDV, hepatitis C (HCV), yellow fever, Sindbis, and vesicular stomatitis (VSV) viruses) independently of IFN production." (PMID 21909274, 2011). "IRF1 is expressed at low levels in unstimulated cells and is activated by many cytokines including type I (IFNα, IFNβ, and others) and II (IFNγ) interferons, tumor necrosis factor-α (TNF-α), retinoic acid, interleukin-1 (IL-1), IL-6, and viral infection." (PMID 22295238, 2011). "However, other individual IRF family members (e.g., IRF-1 or IRF-8), which are known to induce the IFN-β response after viral infection or engagement of PRR in some systems, did not have a dominant regulatory effect in the context of WNV infection." (PMID 19798431, 2009). "Collectively, these results suggest that the antiviral response of IRF1-deficient cells to IFN-α and IFN-γ is only mildly impaired and sufficient to protect IRF1-deficient fibroblasts against viral infection, consistent with the absence of severe viral illnesses in these two patients." (PMID 36736301, 2023). "Interferon regulatory factor-1 (IRF1) is a member of the IFN regulatory factor (IRF) family, which is involved in various physiological and pathological events, including tumor immune surveillance, viral infection, immune system development, proinflammatory injury, and autoimmune diseases." (PMID 35159296, 2022). "Thus, we hypothesized that immune system probably used a similar mode against HIV-1 infection by down-regulated IRF1 and up-regulated IFITM to avert the direct viral infection in CD8+ T cells." (PMID 34580278, 2021). "Whereas pretreatment with IFN-γ significantly decreased viral infection in wild type Mφ, it had virtually no inhibitory effect in IRF-1-/- cells (3.3-, 34- and 116-fold inhibition in wild type cells versus 1.3-, 1.6- and 2.9-fold inhibition in IRF-1-/- cells, P<0.05 at 1, 10 and 100 IU/ml)." (PMID 21909274, 2011). "Interestingly, only minor to moderate reduction in the induction of IRF7, IRF1, VIPERIN, IFIT5, and CMPK2 was observed at 24 hpi, probably reflecting the involvement of IFN-independent mechanisms in regulating the induction of these genes at late stages of the viral infection cycle." (PMID 35891486, 2022). "IRF1, IRF5, and IRF7 can induce the expression of IFIT and IFITM proteins in the absence of viral infections." (PMID 32499867, 2020). "In support of a role for IRF1 in IFN expression, we found that over-expression of IRF1 in a subset of cells rendered the IRF1-nontransduced cells also resistant to viral infection." (PMID 31156620, 2019). "While optimal IFN expression after PRR stimulation may require IRF1, its role in viral infection has been questioned, in part because antiviral defense and IFN expression were not impaired in IRF1 KO mice." (PMID 31156620, 2019).
melanoma (96 papers, 2006 to 2026). A malignant, usually aggressive tumor composed of atypical, neoplastic melanocytes. "The responsiveness of melanoma cells to IFN-γ is associated with the activation of IRF1, which is crucial for the upregulation of PD-L1." (PMID 40108693, 2025). "In melanoma and colon cancer cells, IRF1-deficient tumor cells exhibited reduced growth rates due to the increased cytotoxic properties of CD8 T lymphocytes." (PMID 38396830, 2024). "For example, IRF1 has been shown to be associated with the development of different tumor immune phenotypes in melanoma cell lines." (PMID 38396830, 2024). "Stimulation of the IRF2-deficient melanomas with interferon induced the expression of a functionally homologous transcription factor, IRF1, which then restored the MHC I pathway and responsiveness to CPI." (PMID 39281881, 2024). "The study supports previous observations, which suggested that inhibition of MAPKs sensitizes BRAF-mutated melanoma cells to RIG stimulation through the induction an IRF1-dependent pro-inflammatory program." (PMID 39165562, 2024). "Experiments have demonstrated that the activation of the cDC1-related NF-κB/ Interferon regulatory factor 1 (IRF1) axis is associated with improved clinical outcomes in patients with melanoma." (PMID 38012715, 2023). "CD8+ T cells in IRF1-deficient melanoma showed increased cytotoxicity, the expression of PD-L1 was upregulated, and tumor growth was more easily restored." (PMID 34220795, 2021). "Individual immunotherapy panel markers CD274, PDCD1LG2, CD8A, IRF1 and a combined L1/L2 mRNA levels show promising associations with melanoma immunotherapy outcome." (PMID 31533832, 2019). "Major focus of our study related to the apoptosis of melanoma cells is to understand the mechanism of ceramide generation by cisplatin in PKCδ deficient cell, while IRF-1 and TNFα emerged as key regulatory molecule." (PMID 30701020, 2018). "Activation of IRF-1 in the same melanomas correlated with that of transcripts associated with improved survival in cancer and immune-mediated tissue specific destruction." (PMID 21875439, 2011). "In the group with high levels of IRF1 activation, inhibition of mTOR and Wnt/β-catenin signaling pathways was observed, which was previously shown to be associated with poor prognosis and a more aggressive immune phenotype in melanoma." (PMID 38396830, 2024). "Role of IRF1 in reversing the immune evasion phenotype in IRF2-deficient B16 melanoma cells." (PMID 39281881, 2024). "Lastly, dedifferentiated patient derived melanoma cell lines showed enhanced inflammatory signaling in response to IFNγ compared to differentiated cells, and tended to have higher PD-L1 expression, associated with increased IRF1 expression and activity." (PMID 39736644, 2024). "IFN-γ-dependent activation of the JAK/STAT/IRF1 signaling pathway can induce cytotoxic and cytostatic effects in cancer cells, although it was shown that only a fraction of melanoma cell lines can respond to IFN-γ with potent induction of its typical targets." (PMID 40108693, 2025). "The inhibition of methyltransferase 3, N6-adenosine-methyltransferase complex catalytic subunit (METTL3) enhances the response to anti-PD-1 therapy in melanoma by stabilizing the IFN-γ/STAT1/IRF1 pathway." (PMID 40108693, 2025). "This inhibition occurs through a decrease in the expression and phosphorylation of STAT1, leading to reduced levels of IRF1, a key regulator of PD-L1 and PD-L2, in both human and murine melanoma cells." (PMID 40420174, 2025). "High expression of IFN-γ-related genes, including TBX21, STAT1, IRF1, and IFNG, is associated with better outcomes than anti-PD-1 monotherapy in melanoma patients." (PMID 40108693, 2025).
melanoma (continued). "Previous studies have demonstrated that IFNγ-induced PD-L1 expression is reliant on JAK1/JAK2 activity, and that PD-L1 promoter activity and subsequent expression is mainly influenced by STAT1/STAT3 and IRF1 in IFNγ treated melanoma cells." (PMID 39736644, 2024). "This enhancement occurs through the IFNG-signal transducer and activator of transcription 1 (STAT1)-interferon regulatory factor 1 (IRF1)-LPCAT3-induced ferroptosis pathway in mouse models of melanoma and lung cancer." (PMID 38844964, 2024). "We also found that DRG2 depletion significantly increased the expression of PD-L1 and IRF1 in SK-MEL-28 human melanoma cells and CT26 murine colorectal carcinoma cells." (PMID 38802348, 2024). "Since type II interferon can also induce IRF1, and this cytokine was FDA-approved for other indications, future studies should examine the effects of type II IFN on melanomas that are IRF2-deficient and its potential as an adjuvant therapy with CPI." (PMID 39281881, 2024). "The development of CCR7+DCs from cDC1s is dependent on transcription factor IFN regulatory factor 1 (IRF1), which is proved to be regulated by NF-κB in the maturation of tumor infiltrating cDC1s in melanoma model." (PMID 39493763, 2024). "This is unexpected, as IRF1 is the main transcription factor driving PD-L1 promoter function in melanoma cells, and thus IRF1 knockdown would be anticipated to drastically decrease PD-L1 expression in melanoma cells, irrespective of differentiation state." (PMID 39736644, 2024). "This was an IRF1 target gene set (STTTCRNTTT_IRF_Q6), which implicates increased IRF1 activity with high PD-L1 expression in dedifferentiated melanoma cells, similar to what we observe in the 624Mel cell line." (PMID 39736644, 2024). "Inhibition of the JAK kinases, NF-κB and STAT3 with small molecule inhibitors, and siRNA mediated knockdown of STAT1 and IRF1 was applied to investigate the molecular mechanism behind IFNγ induced PD-L1 expression in dedifferentiated melanoma cells." (PMID 39736644, 2024). "To further evaluate the role of IRF1 in vivo, we examined the therapeutic effect of anti-PD1 + poly(I:C) treatment on IRF1 + IRF2 double knockout melanoma cells." (PMID 39281881, 2024). "We have mentioned in the section 3.5, in melanoma model, NF-κB regulate the transcription factor IRF1,which is essential in the development of CCR7+DCs from cDC1s." (PMID 39493763, 2024). "Conversely, IRF1 was also found to be a tumor promoter in colon adenocarcinoma, melanoma, and endometrial cancer." (PMID 38789431, 2024). "Last but not least, ATXN3 positively correlated with expression of PD-L1 and its transcription factors HIF-2α and IRF1 in both human lung adenocarcinoma and melanoma tissues." (PMID 38038129, 2023). "TLR5 can effectively alleviate the stimulation caused by radiation, and SOX10 independently regulates the expression of IRF1 in melanoma through the JAK-STAT signaling pathway." (PMID 37113996, 2023). "This included the interferon regulatory factor 4 (IRF4), a transcription factor known to be induced by SOX10 that acts as a negative regulator of IRF1 to repress melanoma immunogenicity." (PMID 36434616, 2022). "Another example is the selncRNA-associated IFN-γ signaling pathway, which substantially increases PD-L1 expression in melanoma cells by activating the JAK/STAT/IRF1 axis in melanoma cells." (PMID 36612180, 2022). "PD-L1 is regulated by interferon-γ (IFNγ) signaling and displays interferon regulatory factor 1 (IRF1) binding at its promoter, as described in melanoma cells and other cancer entities." (PMID 34689158, 2021). "The expression of PD-L1 is regulated by the IFNγ/STAT1/IRF1 axis in melanoma cells; IRF1 binds directly to the PD-L1 promoter." (PMID 33476326, 2021).
melanoma (continued). "We confirmed that this effect was driven by inhibiting STAT1 gene expression and STAT1 phosphorylation, thereby downregulating the PD-L1/PD-L2 transcriptional regulator IRF1 in both human and mouse melanoma cells." (PMID 34832863, 2021). "Only the module turquoise had a significant enrichment (p = 0.009) of genes whose homologs displayed prognostic value in melanoma, such as Oca2, Samhd1, Nlrc5, Irf1, Ifitm3, Sp100, Dram1, Rtn1, Tcaf2, Parp10, and Grin3a." (PMID 32831131, 2020). "The high expression of IRF1, JAK2, CD8A, STAT5B, and SELL was connected with a low risk of death and was a protective factor of melanoma." (PMID 32316408, 2020). "To assess the mRNA expression of four immunotherapy markers, CD274, PDCD1LG2, CD8A and IRF1, we used a multiplex RT-qPCR immunotherapy panel on the GeneXpert platform in melanoma patients treated with anti-PD-1 therapy." (PMID 31533832, 2019). "Our previous results suggest a positive regulatory role of IRF1-TNFα interactions in ceramide generation leading to apoptosis in PKCδ silenced B16F10 mouse melanoma cells." (PMID 30701020, 2018). "A recent study confirmed that PD-L1 expression in melanoma cells is mainly regulated by the IFN-γ receptor signaling pathway which subsequently converged to the binding of IRF1 with the PD-L1 promoter." (PMID 30333036, 2018). "Attenuation of IFNγ-induced PD-L1 expression in melanoma cells was proven to happen via down-regulation of the Jak/STAT/IRF-1 signaling pathway, while activation of Jaks led to PD-L1 up-regulation in hematopoietic tumor cell lines and primary tumor cells." (PMID 30356906, 2018). "The key role of IRF1 and interferon receptor pathway in the regulation of PD-L1 has also been implied in melanoma, where putative binding sites for IRF1 have been identified in the PD-L1 promoter and abrogation of IRF1 site resulted in reduced PD-L1 levels." (PMID 29765155, 2018). "To determine if there was biologic significance to this cutpoint, we determined the limit of detection for IRF-1 by staining five serum-starved melanoma cell lines for IRF-1 and identifying the lowest AQUA score a FOV with positive nuclear staining." (PMID 28331615, 2017). "This study is this first report of IRF-1 as a tissue-based biomarker to predict response to anti-PD-1 immunotherapy in melanoma." (PMID 28331615, 2017). "Compared to PD-L1 status, nuclear IRF-1 staining better predicted objective radiographic response and progression-free survival in a retrospective cohort of 47 melanoma patients." (PMID 28331615, 2017). "While IRF-1’s role in regulating an inflamed melanoma phenotype has been previously characterized, this is the first report of IRF-1 as a predictive tissue biomarker to anti-PD-1 immunotherapy in melanoma." (PMID 28331615, 2017). "Accordingly, analyses on TCGA melanomas revealed a strong association between patient survival and elevated mRNA levels of STAT1 and its downstream target IRF1, indicating IFNγ-dependent pathway activation." (PMID 28561041, 2017). "Recently, an unexpected connection between the immune cytokine ifnγ and skin pigmentation homeostasis was found mediated through the transcription factor irf1, a gene that we find consistently downregulated in the melanoma developing medaka." (PMID 26714172, 2015). "JAK/STAT induces an ensemble of interferon-stimulated genes including IRF-1, which has been shown to cooperate with NF-κB transcription factors to induce the expression of iNOS in melanomas." (PMID 26265053, 2015). "Consistent with the previous results, IL-27 induced IRF-1 expression at the mRNA level in all three human melanomas." (PMID 24155891, 2013). "We previously demonstrated that IL-27 induces IRF-1 expression, which is involved in the inhibition of tumor growth, in mouse melanoma B16F10 cells ectopically expressing WSX-1." (PMID 24155891, 2013).